MIR4314 (microRNA 4314)
Synonyms: hsa-mir-4314
Gene: MicroRNA gene on chromosome 17 (8,088,056 to 8,088,147, forward strand). Ensembl gene ENSG00000264005.
Homologues: Orthologues: chimpanzee MIR4314 (100% identical).